IL1B (interleukin 1 beta)
Diseases named in the same sentence as IL1B in open-access papers (continued):
Sharing a sentence is not in itself a finding about the gene and the disease.
tumor (continued). "Increased expression of GSTO1-1 and GSTO2-2 was demonstrated in tumor compared to corresponding non-tumor tissue (p = 0.002, p = 0.007, respectively), while GSTO1 expression was correlated with interleukin-1β (IL-1β)/pro-interleukin-1β (pro-IL-1β) ratio (r = 0.260, p = 0.350)." (PMID 31861116, 2019). "To determine whether the IL-1β module acts directly on the tumour cells, we silenced Il1r1 in Py8119 cells and found no impairment of tumour growth in DIO mice, indicating that IL-1β does not primarily act on cancer cells." (PMID 27708283, 2016). "As expected, the involvement of tumor microenvironment in cancer and in its complications, such as DVT, is emphasized in the correlation between plasma levels of IL-6,TNF-α, IL-1β, VEGF and MMP-9 from cancer patients with and without DVT and those released from monocytes." (PMID 26192925, 2015). "Interestingly, q-PCR revealed that the expression levels of IL-1β, IL-6 and MIP-2 as well as IFN-γ and TNF (data not shown) in the colonic tissue, especially in the tumor area, were suppressed by the treatment with ML-7 as well as with MP6-XT22." (PMID 24520376, 2014). "IL-1β and TGF-β did not increase the CXCL7 expression in comparison with CTVT cells alone while IL-6 significantly down-regulated the expression of CXCL7 in tumor cells." (PMID 23136963, 2012). "Although IL-1β was not a strong stimulant of EMT, it is possible that this cytokine supports tumor recurrence or metastasis by other means, such as increased angiogenesis, as indicated by several published studies, or by having joint activity with other factors." (PMID 21486440, 2011). "Macrophages and IL-1β failed to inhibit TRAIL-induced apoptosis in HCT116 cells expressing dnIκB, dnAKT or dnTCF4, confirming that they oppose TRAIL-induced cell death through induction of Wnt signaling in tumor cells." (PMID 20661477, 2010). "Consistent with our observation that macrophages/IL-1β induce Wnt signaling in an NF-κB dependent manner, we showed that macrophages and IL-1β failed to inhibit TRAIL-induced apoptosis in tumor cells expressing dnIκB, confirming the oncogenic role of NF-κB signaling." (PMID 20661477, 2010). "The results showed that the expression levels of FLT3LG, GALNT10, IL1B, IMPDH1 and ISG20 were higher in tumor cells than in normal cells, while the remaining genes could not be identified because of the low expression levels in tumor cells." (PMID 36816023, 2023). "Furthermore, tumour cells and non-malignant stromal cells secrete different growth factors such as TGF-β1, EGF, vascular endothelial growth factor (VEGF), FGF, TNF-α, IL-1β, and IL-6 that promote CAF trans-differentiation and activation, contributing to a pro-inflammatory profile and carcinogenesis." (PMID 34830058, 2021). "Despite the fact that TNFα and IL-1β induced potent p65 and JNK activation in T47D and MCF-7 luminal-A cells, CXCL8 levels were not increased but rather were decreased when the tumor cells interacted with MSCs in the presence of TNFα and IL-1β (Figures 6B1, 7B)." (PMID 31031757, 2019). "Indeed, macrophages with silenced IL-1β or STAT1 or vitamin D3 treated macrophages, which failed to protect tumor cells from TRAIL-induced apoptosis, also failed to stabilize Snail in tumor cells." (PMID 20661477, 2010). "However, our study does not exclude the possibility that secretion of IL-1β from PAAD cells, as observed in our study, has no autonomous action on tumor cells itself, which means that we did not completely rule out the possibility that IL-1β secretion can affect tumor cell expansion and spread." (PMID 34150748, 2021). "Furthermore, the expression of cytokines IL-1β and IL-6 in the GC + PTT group was both 1.7-fold higher than that in the PBS + PTT group, whereas, the expression of the cytokine IL-4 with a pro-tumor function was not significantly different between all the groups." (PMID 32042338, 2020).
cancer (1,826 papers, 1993 to 2026). A tumor composed of atypical neoplastic, often pleomorphic cells that invade other tissues. "The NLRP3 inflammasome, which processes pro-inflammatory cytokines IL-1β and IL-18, has been implicated in cancer-related inflammation, and preliminary data indicate that dietary polyphenols can inhibit inflammasome activation." (PMID 41226270, 2025). "Aberrant NLRP3 activation is associated with various types of human cancer; its detrimental effects are attributed mainly to its effector cytokine IL-1β." (PMID 40794443, 2025). "Interleukin- 1β (IL-1β) is a proinflammatory cytokine that regulates heterogeneous cancer associated fibroblast (CAF) phenotype and promotes an immunosuppressive TME." (PMID 39948655, 2025). "IL-1α and IL-1β are key downstream factors in intrinsic and extrinsic pathways linked to inflammation and malignant tumors." (PMID 41333471, 2025). "First, IL-1β not only triggers acute inflammatory responses but also promotes chronic inflammation, a well-known cancer risk factor." (PMID 40356762, 2025). "Mutated TNF-α can directly contribute to cancer formation, while cytokines such as IL-6, IL-8, and IL-1β stimulate cell proliferation and cervical cancer progression." (PMID 40430101, 2025). "Instead, the same authors previously demonstrated that anthracycline-induced ICD is associated with the release of IL-1β and priming of anti-cancer CD8+ T cells." (PMID 39857785, 2025). "A longitudinal study of 71 cancer survivors suggested that attenuation in IL-1β, IL-6, TNF-α, and IL-10 was associated with either an increased sleep duration or decreased sleep problems." (PMID 41470834, 2025). "This dual modulation of IL-1β suppression and IL-18 activation highlights unique advantage of plant-derived EVs in targeting cancer-associated inflammation." (PMID 40604924, 2025). "Three cytokines, IL-6, TNF-α, and IL-1β, serve as central mediators of cancer-associated hypercoagulability through distinct but overlapping mechanisms." (PMID 40725619, 2025). "The recruitment of neutrophils was associated with the expression and secretion of IL-1β from cancer cells, and the involvement of this specific cytokine was verified by the absence of anti-metastatic effects of LY500307 in IL-1β knockout mice." (PMID 39175529, 2024). "IL-1β and IL-6, in particular, are associated with cancer, promoting cancer initiation and progression." (PMID 39340596, 2024). "We measured IL-6, TNFα, and IL-1β, which are risk factors for cancer development and are also involved in HIV-1 pathogenesis." (PMID 38166062, 2024). "Although some reports have shown a relationship between IL‐1β polymorphisms and the development of malignant tumors, reports showing a relationship with prognosis are extremely rare." (PMID 38798075, 2024). "These nsSNPs can be considered significant candidates in the pathogenesis of disorders and cancers caused by IL1B dysfunction, contributing to effective drug discovery and the development of precision medications." (PMID 38858637, 2024). "While the release of IL-1β is directly linked to the progression of several types of cancers, the role of GSDMD in cancer is less clear." (PMID 39224600, 2024). "IL-1β is a pro-inflammatory mediator that is frequently upregulated in a variety of cancers, and its production is associated with poor prognosis." (PMID 39456771, 2024). "IL-1β was associated with vascular invasion (210 vs. 183, p < 0.02), lymphatic invasion (210 vs. 180, <0.05) and G3 cancer (192 vs. 188, <0.04)." (PMID 38397123, 2024). "Genetic variants in IL-1β, such as rs1143627 and rs16944, have been associated with various inflammatory diseases and breast and cervical cancers." (PMID 39766795, 2024).
cancer (continued). "Increased inflammatory cytokines in cancer cachexia, such as interleukin (IL)-1β, IL-6, and Tumor Necrosis Factor-α (TNF-α), cause lipid degradation and reduced lipid synthesis." (PMID 39272951, 2024). "IL1B showed marked increases in the cancer group, highlighting their association with tumorigenesis and inflammation, consistent with previous findings." (PMID 39523395, 2024). "IL-1β is secreted by macrophages and is known to be associated with migration and invasion of cancer cells." (PMID 38188678, 2023). "Deregulated IL-1β release is linked to cancer and inflammatory conditions that affect major organs, including the vasculature, brain, liver, skin, gut, and joints." (PMID 37474493, 2023). "Extensive research has been conducted on the role of cancer-associated fibroblasts (CAFs) in solid tumors, particularly in relation to their production of soluble factors such as IL-1α, IL-1β, CXCL1, CXCL12, G-CSF, and IL-6." (PMID 37880682, 2023). "Next, we measured the levels of cyclooxygenase-2 (COX-2), an inducible enzyme associated with immunosuppression and Th2 polarization in cancer and known to be regulated by IL1β." (PMID 37772994, 2023). "IL-1b is a pro-inflammatory mediator often upregulated in various types of cancer, and its production is associated with a poor prognosis." (PMID 37760608, 2023). "Cancer-associated fibroblasts are another subset of cells that sense DAMPs and secrete IL-1β through the inflammasome pathway." (PMID 36932407, 2023). "A recent study indicated that mice with EGFR mutations are more likely to develop cancer after exposure to pollutant particles mediated by an inflammatory protein called interleukin 1 beta, which is part of the body's immune response to PM2.5 exposure." (PMID 36975376, 2023). "Inflammatory factors can modulate the response of cancerous cells to chemotherapy, and anti-cancer drugs can cause the expression of some of the cytokine genes, including those of TNFα, IL-1β, and IL-6." (PMID 36834426, 2023). "This notion is reinforced by additional research demonstrating the role of IL-1β and its strong association with cancer cachexia." (PMID 37755304, 2023). "We next injected C57BL/6 mice competent (WT) and diploinsufficient for Il1b alleles (Il1b−/−) with syngeneic cancer cell lines carrying KrasWT and KrasMUT alleles." (PMID 36980752, 2023). "We examined the association between TonEBP and IL-1β, both closely associated with cancer cell migration and invasion." (PMID 38188678, 2023). "In this Northeastern-Chinese case–control study, we examined three htSNPs tagging 95% of the haplotyping diversity of IL1B known to be involved in the inflammatory response and associated with cancer risks in previously studies." (PMID 37147350, 2023). "Alternative mechanisms explain BRAFi resistance by a cytokine-signaling network involving TAM-derived IL-1β, cancer-associated fibroblasts (CAFs)-derived CXCR2 ligands, and PTEN inactivation." (PMID 37511306, 2023). "For this, we first searched TCGA pan-cancer transcriptomes (n = 10,071) for associations between mRNA levels of IL1B and established cancer and immune cellular lineage markers." (PMID 36980752, 2023). "Several genes and gene products were identified as targets of miR-223, including NLRP3, IL18, IL1β, DNA methyltransferase 1, and checkpoint kinase-1, signifying its potential use as a cancer-specific diagnostic biomarker and therapy." (PMID 35205115, 2022). "Studies have shown that alterations in genes encoding pro-inflammatory cytokines (IL-1β, IL-6) and their high concentrations greatly contribute to the occurrence, intensity, and severity of various symptoms in cancer patients." (PMID 36067147, 2022). "The increase in CD47 by exogenously supplied IL-1β and GM-CSF also sufficed to overcome the enhanced sensitivity of cancer cells to phagocytosis caused by knockdown of SIRPγ." (PMID 35229723, 2022).
cancer (continued). "Many patients with cancer cachexia suffer from inflammation associated with elevated cytokines, such as interleukin-1beta (IL-1β), interleukin-6 (IL-6), and tumor necrosis factor (TNF)." (PMID 36358681, 2022). "M2 macrophages, which are associated with cancer progression and invasion secret increased IL-1β under conditions of FAO dependence and HIF-1α upregulation." (PMID 35902970, 2022). "CCL22 expression in oral cancer cells was induced by IL-1β secreted by cancer-associated fibroblasts, suggesting a new therapeutic prospect by targeting the IL-1β-CCL22-CCR4 signaling axis for the treatment of oral cancer." (PMID 34177907, 2021). "Inflammatory conditions can lead to increased expression of inflammatory cytokines, including interleukin-6, TNF, and IL-1β, which increase the risk of cancer." (PMID 34239566, 2021). "IL-1β is released from macrophages and along with its potent inflammatory effect it has been widely established that IL-1β production is upregulated in ovarian, lung, and GI cancers and in general these cancers are associated with bad prognoses." (PMID 33907915, 2021). "The exposure of mesenchymal stem cells to the proinflammatory cytokines, tumor necrosis factor-alpha (TNF-α) and interleukin-1 beta (IL-1β) can lead to the development of the cancer-associated fibroblast (CAF) phenotype." (PMID 34638283, 2021). "Constitutive activation of caspase-1 in EBV-associated cancer facilitates viral genome persistence and immune evasion via cleavage of the pro-forms of IL-1β and IL-18." (PMID 33918087, 2021). "An earlier study that evaluated the association between proinflammatory cytokines and cancer incidence revealed that IL-1β, IL-6, and TNF-α are associated with an increased risk of cancer." (PMID 33869169, 2021). "Such auto amplification of IL-1β is found to involve NLRP3 inflammasome activation in cancer-associated macrophages." (PMID 34588926, 2021). "Caspase 1 enzymatically converts the inactive form of IL-1β, pro-IL-1β, to its active form, IL-1β, and increases in IL-1β are associated with aging and diverse cancers." (PMID 34572547, 2021). "Recent studies have shown that FAPs can undergo senescence, and IL-1β is a well-established component of the senescence-associated phenotype (SASP) which partly explains it’s role in cancer cachexia." (PMID 35047502, 2021). "We found that the IL-6- and IL-1B-encoding genes were dramatically overexpressed in CD4+ T cells due to exhaustion induced by cancer cells." (PMID 34439305, 2021). "IL-1β is primarily derived from myeloid cells and is upregulated and associated with disease progression in many different types of cancer, such as colon and lung malignancies." (PMID 34386015, 2021). "Experimental or clinical studies show promising therapeutic results by targeting IL-1β signaling for a broad spectrum of disorders including cardiovascular disease and cancer treatment-associated life-threatening cytokine release syndrome." (PMID 32070376, 2020). "In particular, the NLRP3 inflammasome has been implicated in cancer development, given its ability to activate the pro-inflammatory cytokines IL-1β and IL-18 which cause metabolic, inflammatory, hematological, and immune effects." (PMID 33014808, 2020). "IL-1β was shown to increase PD-L1 at the membrane of cancer cells and CAFs, and associations of antibodies targeting IL-1β and PD-1 have shown promising therapeutic efficacy." (PMID 33261061, 2020). "In the present study, we further revealed that the exacerbation of NLRP3 inflammasome activation by ABHD5 deficiency, provides a positive feedback loop to promote cancer progression by preferentially secrete the proinflammatory cytokine IL-1β." (PMID 32867817, 2020). "Further studies showed that the exacerbation of NLRP3 inflammasome activation by ABHD5 deficiency, provides a positive feedback loop to promote cancer progression by preferentially secrete the proinflammatory cytokine IL-1β." (PMID 32867817, 2020).
cancer (continued). "Among the inflammatory conditions involved in acquired drug resistance, the secretion of interleukin-1β (IL-1β) has been implicated as a critical mediator in human cancers." (PMID 32899791, 2020). "Overall, cytokines are divided into proinflammatory groups such as TNF-α, IL-1β, IL-2, and IL-6, which play a role in initiating chronic inflammation and activating the NF-κB pathway and are strongly linked to cancer growth." (PMID 32156252, 2020). "On the one hand, different from those in the HD-MSCs group, AA-MSCs highly expressed proinflammatory and cancer-associated genes (IL1B, IL-24, CXCLs, FOS, KLK10)." (PMID 32054519, 2020). "IL-1β is considered to be indicators of an increased risk of carcinoma and poor prognoses in multiple cancers." (PMID 32867817, 2020). "IL-1β-induced inflammation is considered a risk factor related to the acquisition of an aggressive phenotype in cancer cells." (PMID 30641908, 2019). "In other analyses, increased IL-1β expression was related to a greater risk of developing different types of cancer, because it causes tumorigenesis, angiogenesis and metastasis through different mechanisms." (PMID 31554368, 2019). "IL‐1β was found to be elevated in various types of cancers, and IL‐1β producing tumors have been associated with bad prognosis (Danis, Millington, Hyland, & Grennan, 1995)." (PMID 31297985, 2019). "The molecular mechanisms underlying the role of the IL-1β signaling pathway in cancer chemoresistance have been disclosed." (PMID 31492049, 2019). "Taken together, our study demonstrates that IL-1β is a targetable factor that drives cancer-associated thrombosis, possibly by modulating G-CSF production and facilitating NET formation." (PMID 31552036, 2019). "Interleukin-1β (IL-1β) modulates the expression of granulocyte colony-stimulating factor (G-CSF), a cytokine that promotes cancer-associated neutrophilia and NET generation." (PMID 31552036, 2019). "The results showed that an increase in the risk of progression of pre-neoplastic lesions to cancer was between 2.5 and 2.08 times higher in women with lower IL-1β and IL-18 expression, respectively." (PMID 31554368, 2019). "Catabolic pro-inflammatory cytokines associated with cancer cachexia include interleukin-6 (IL-6), interleukin-1 beta (IL-1B), tumor necrosis factor alpha (TNF-α), and interferon gamma (IFN-γ)." (PMID 30591621, 2018). "Recent reports suggested that most of the pro-inflammatory cytokines, including IL-2, IL-6, IL-1β and IL-10, are over-expressed at cancer specific sites and particularly linked to invasion and progression of sever HCC conditions." (PMID 29651140, 2018). "Loss of IRF6 and IL-1β function during cervical neoplastic stages reflects a prognostic read out towards cancer development." (PMID 30089163, 2018). "CCL7 secretion is increased after IL-1β produced by cancer cells activates the NF-κB signaling pathway in cancer-associated fibroblasts (CAFs)." (PMID 29915688, 2018). "The IL-1β inflammatory cytokine encoded by IL1B plays a critical role in cancer progression, particularly in colorectal cancer." (PMID 30218041, 2018). "IL-1 is the most extensively characterized inflammasome-related cytokine promoting cancer, whereas IL-1β is a pleiotropic inflammatory cytokine associated with cell proliferation, differentiation, tissue regeneration, and immune cell regulation." (PMID 30631327, 2018). "IL-1β polymorphisms were also linked to several kinds of malignant tumors, such as gastric cancer, hepatocellular carcinoma and lung cancer." (PMID 29312552, 2017). "Increased cell proliferation of these cancer cell lines was contributed to by interleukin 1-beta (IL1-β) mediated mitogen associated protein kinase (MAPK) signaling." (PMID 28425934, 2017). "Clinical studies have provided evidence that the measurement of IL-1β and IL-18 correlates with the risk of carcinoma and the prognosis of established cancer including prostate." (PMID 28663562, 2017).